TRPC6 (transient receptor potential cation channel subfamily C member 6)
Diseases named in the same sentence as TRPC6 in open-access papers (continued):
Sharing a sentence is not in itself a finding about the gene and the disease.
psoriasis (4 papers, 2011 to 2026). An autoimmune condition characterized by red, well-delineated plaques with silvery scales that are usually on the extensor surfaces and scalp. "Results elucidated that the mRNA level of TRPC6 in psoriasis skin lesions decreased compared with normal people, however, the statistical difference needs further verification (data not show)." (PMID 34025642, 2021). "We have also used the data in the GEO database to perform differential gene analysis to clarify the exact changes of mRNA levels of TRPC6 channels in psoriasis skin lesions." (PMID 34025642, 2021). "Recently, other group detected mRNA expression levels of TRP channels in PBMCs of 30 patients with psoriasis, data showed that in the patient group, the TRPC6 expression levels were lower compared to controls." (PMID 34025642, 2021). "As TRPC6 channel activation could partially overcome this Ca2+ entry defect in psoriasis keratinocytes, specific TRPC6 channel activators e.g. out of the phloroglucinol class may be potential new drug candidates for the topical treatment of psoriasis." (PMID 21364982, 2011). "Margarethe Muller had reported that hyperforin modulates the differentiation and proliferation of HaCaT cells and primary cultures of human keratinocytes via TRPC6 channels by inducing Ca2+ influx, which may be partially involved in the pathogenesis of psoriasis." (PMID 34025642, 2021). "The hypothesis that TRPC channels might be a novel target for the treatment of psoriasis is supported by our findings that specific TRPC6 activation by hyperforin not only elevates [Ca2+]i but also at least partially overcomes the intrinsic defect of maturation." (PMID 21364982, 2011). "Similarly, the stainings for TRPC4 and TRPC6 were also weaker in psoriasis lesions." (PMID 21364982, 2011). "Growing evidence suggests the involvement of multiple TRP subtypes in the pathogenesis of psoriasis, including altered expression of vanilloid subtypes, such as TRPV1, TRPV3, TRPV4, TRPV6, the canonical TRPC6, and melastatin TRPM8 in patients." (PMID 41689746, 2026). "Similarly, hyperforin, the major lipophilic active ingredient of HP, stimulates calcium influx into psoriasis HPK, activates the expression of the transient receptor potential cation channel, subfamily C, member 6 (TRPC6), and promotes proper cell differentiation." (PMID 33801280, 2021).
renal cell carcinoma (4 papers, 2022 to 2025). "Both the functional acquired mutation and overexpression of TRPC6 can lead to kidney diseases, such as focal and segmental glomerulosclerosis, fibrosis and renal cell carcinoma." (PMID 37576896, 2023). "From a pathophysiological point of view, evidence is provided showing the involvement of TRPC6 in renal cell carcinoma emergence and progression." (PMID 36613622, 2022). "In renal tubule cells, TRPC6 channels might be involved in several pathophysiological states, such as ischemia–reperfusion injury, as well as in tumorigenesis and progression of renal cell carcinoma, which predominately originates from the proximal tubule." (PMID 41373637, 2025). "However, TRPC6 seems to be involved in tumorigenesis of renal cell carcinoma." (PMID 36613622, 2022). "Therefore, TRPC6-NFATc1 pathway mediated by WNK1-PI4KIIIa through PLC-β signal may play a key role in the tumor growth of ccRCC, and this mechanism can provide a potential new target for the treatment of renal cell carcinoma in the future." (PMID 37576896, 2023).
Sepsis (4 papers, 2016 to 2024). Sepsis is defined as life-threatening organ dysfunction caused by a dysregulated host response to infection. "Potential treatments could target TRPC6 to control the release of cytokines in sepsis and inhibit abnormal calcium signaling in cancers such as B-cell lymphomas." (PMID 39161881, 2024). "TRPC6 knockout dampens Th2-driven hypersensitivity responses in sensitised mice after airway allergen re-challenge while sustained inward calcium currents due to TRPC6 may be indispensable for antimicrobial T cell responses during sepsis." (PMID 29973568, 2018). "Moreover, TRPC6 deletion in mice increased resistance to endotoxin-induced barrier dysfunction and inflammation, and protected against sepsis-induced lethality." (PMID 28400714, 2017).
status epilepticus (4 papers, 2019 to 2022). Status epilepticus is defined as a continuous seizure lasting more than 30 min, or two or more seizures without full recovery of consciousness between any of them. "Although TRPC6 knockdown evokes the massive DGC degeneration induced by status epilepticus (a prolonged seizure activity, SE), the molecular mechanisms underlying the role of TRPC6 in DGC viability in response to SE are still unclear." (PMID 31683954, 2019). "There is evidence that TRPC6 may partly contribute to neuronal death in the DG in pilocarpine-induced status epilepticus." (PMID 34489621, 2021). "In status epilepticus, TRPC6 serves to protect granule neurons of dentate gyrus from degeneration through activation of ERK1/2 and the subsequent phosphorylation of dynamin-related proteins 1 (DRP1) at Ser-616 and an increase in the expression of a mitochondrial protease, Lon protease-1." (PMID 33490083, 2020). "In a rodent model of pilocarpine-induced status epilepticus, while the expression of TRPC3 was found to be increased, that of TRPC6 was decreased in CA1 and CA3 pyramidal neurons and dentate granule cells." (PMID 33490083, 2020). "Transient receptor potential canonical channel-6 (TRPC6) is one of Ca2+-permeable non-selective cation channels, which protects neurons from ischemia, excitotoxicity, and status epilepticus (a prolonged seizure activity, SE)." (PMID 31683954, 2019).
B-cell lymphomas (3 papers, 2015 to 2024). "Gene expression analysis of B cell lymphomas revealed that the TRPC6 gene expression is almost completely reduced, together with other genes located in the same region." (PMID 34065398, 2021).
brain injury (3 papers, 2019 to 2021). Acute and chronic (see also brain INJURIES, CHRONIC) injuries to the brain, including the cerebral hemispheres, CEREBELLUM, and brain STEM. "Inhibitors of TRPC6, such as larixyl acetate and GsMTx4, have been shown to have protective actions against traumatic brain injury and myocardial infarction." (PMID 33669830, 2021). "In this study, the involvement of TRPC6 channel activation in mediating traumatic brain injury-induced aortic endothelial dysfunction was validated using a specific inhibitor of TRPC6, larixyl acetate." (PMID 32872338, 2020). "The role of TRPC6 in bone marrow stromal cell (BMSC) transplant was investigated, where the application of BMSCs overexpressing TRPC6 reduced brain injury in a rat IR model." (PMID 33669830, 2021).
breast adenocarcinoma (3 papers, 2008 to 2018). "Immunohistochemical analysis of 49 normal tissues and ductal breast carcinomas has revealed that TRPC6 is overexpressed in breast adenocarcinoma." (PMID 30223530, 2018).
cervical cancer (3 papers, 2022 to 2023). A primary or metastatic malignant neoplasm involving the cervix. "The expression of TRPC6 in cervical cancer tissues is greater than in normal cervical tissues, and verapamil, a calcium channel antagonist, has been found to reduce the invasiveness of HeLa cells by co-culture in HeLa cells." (PMID 35392906, 2022). "An increased TRPC6 channel in cervical cancer cell lines induces cell proliferation, suggesting that channel inhibition might reduce the malignant behavior of the cancer." (PMID 37892239, 2023). "The TRPC6 gene and its protein were also expressed in cervical cancer HeLa cells." (PMID 35392906, 2022). "The high expression of calcium channel TRPC6 in HeLa and SiHa tissues may be related to the malignant behavior of cervical cancer cell lines HeLa and SiHa." (PMID 35392906, 2022). "TRPC6 might be a new target for the prevention and treatment of cervical cancer." (PMID 37892239, 2023). "TRPC1 and TRPC6 mutations mainly occurred in cervical adenocarcinoma, while TRPC4, TRPV and TRPM were mainly mutated in cervical squamous cell carcinoma, which indicated that TRPs mutations could be one of the causes of cervical cancer." (PMID 36072430, 2022). "The increased expression of TRPC6 may be involved in the progression of cervical cancer." (PMID 36072430, 2022). "The previous study results of our group showed that TRPC6 was significantly higher in cervical cancer tissue than normal cervical tissue." (PMID 35392906, 2022).
colorectal cancer (3 papers, 2018 to 2025). A primary or metastatic malignant neoplasm that affects the colon or rectum. "lncRNA TUG1 promoted the proliferation and migration of colorectal cancer cells through the miR-145-5p/TRPC6 pathway, EMT pathway, miR-26a-5p/MMP14/p38MAPK/Hsp27 axis, Twist1/EMT signal pathway, or by overexpression." (PMID 34039257, 2021). "It would be interesting to define the role of endothelial TRPV channels in angiogenesis and carcinogenesis as recent published data implies that TRPV3, TRPV4, TRPV5, TRPM4 and TRPC6 may be thought of as potential genes contributing to colorectal cancer tumorigenesis." (PMID 29914124, 2018).
congestive heart failure (3 papers, 2022 to 2024). Failure of the heart to pump a sufficient amount of blood to meet the needs of the body tissues, resulting in tissue congestion and edema. "The enhancement of TRPC6-specific Zn2+ influx will be a new therapeutic target of chronic heart failure." (PMID 36289215, 2022). "Pharmacological enhancement of TRPC6-mediated Zn2+ influx prevents chronic heart failure progression in mice." (PMID 36289215, 2022). "Transient receptor potential 6 (TRPC6) gene alterations are putative risks for chemotherapy-induced congestive heart failure, and TRPC6 N338S is a gain-of-function mutant that may lead to DIC by increasing Ca2+ influx within cardiomyocytes [34•]." (PMID 38676836, 2024). "Our data demonstrate that TRPC6-mediated Zn2+ influx with α1AR stimulation enhances baroreflex-induced positive inotropy, which may be a new therapeutic strategy for chronic heart failure." (PMID 36289215, 2022). "We finally examined whether activation of the α1AR-TRPC6-βAR axis improves positive inotropy and chronic heart failure through TRPC6-mediated Zn2+ influx." (PMID 36289215, 2022). "Notably, we demonstrated that increased TRPC6 channel activity or enhanced αAR-TRPC6-βAR coupling improves βAR-dependent cardiac positive inotropy and chronic heart failure in mice, which suggests a novel pathophysiological role of TRPC6 in the heart." (PMID 36289215, 2022). "Our results do not completely rule out the effect of TRPC6-mediated Ca2+ influx, but strongly suggest that α1AR-mediated Zn2+ mobilization through TRPC6 channels potentiates NE-induced cardiac positive inotropy, which may lead to improvement of chronic heart failure." (PMID 36289215, 2022). "Therefore, in this work we assessed whether TRPC6-mediated Zn2+ influx physiologically contributes to the sympathetic nerve–activated cardiac positive inotropic response by enhancing βAR/Gs-dependent signaling and whether it has a beneficial effect on chronic heart failure." (PMID 36289215, 2022).
endometriosis (3 papers, 2018 to 2021). The growth of functional endometrial tissue in anatomic sites outside the uterine body. "Analogously, 100 μM OAG was used to assess TRPC6 functionality, what resulted in an influx in intracellular calcium of 480 ± 198 nM in 32 ± 25% of the endometriosis-derived hESC responders (total of 114 cells)." (PMID 30134548, 2018). "Additionally, TRPV2, TRPV4, TRPC1/4, and TRPC6 were found in human endometrial stromal cells (hESCs) from patients with endometriosis." (PMID 34337010, 2021). "Additionally, and in line with previous reports of control patients, TRPV2, TRPV4, TRPC1/4, and TRPC6 were present in human endometrial stromal cells (hESC) from endometriosis patients both at the molecular and functional level." (PMID 30134548, 2018).
glaucoma (3 papers, 2022 to 2024). Increased pressure in the eyeball due to obstruction of the outflow of aqueous humor. "However, recent research reported elevated levels of TRPC1/TRPC6 channel proteins in glaucoma lamina cells (LC) compared to LC cells from healthy donors." (PMID 35185615, 2022). "In conclusion, it is reasonable to suppose that the TRPC6 plays a key role in glaucoma." (PMID 35185615, 2022). "Although there is currently no direct evidence linking STIM1/2 with glaucoma, TRPC1 and TRPC6 channels, which are known interacting partners of STIM isoforms, were upregulated in glaucomatous lamina cribrosa leading to NFAT4-mediated gene expression remodeling." (PMID 39424970, 2024).
glomerulonephritis (3 papers, 2021 to 2025). A renal disorder characterized by damage in the glomeruli. "TRPC6 inactivation in rats resulted in the protection of glomeruli in the animal model of severe glomerulonephritis." (PMID 41009007, 2025).
idiopathic membranous glomerulopathy (3 papers, 2014 to 2018). "TRPC6 expression is upregulated in renal biopsies of patients with idiopathic membranous glomerulopathy (iMN) and animal models thereof." (PMID 25019165, 2014).
liver cancer (3 papers, 2018 to 2022). An epithelial or non-epithelial malignant neoplasm that arises from the liver. "Studies have shown that the expression of TRPC6 is significantly increased in the hypoxic environment of liver cancer cells." (PMID 36187789, 2022). "TRPC6 is expressed at low levels in normal hepatocytes, but is highly expressed in liver cancer samples." (PMID 36187789, 2022). "In this study, liver cancer 1MEA cells were also found to overexpress TRPC6 and TRPV6 channels, and immunofluorescence studies showed that Tv1 co-localized with these channels." (PMID 31627357, 2019). "In this study, Tv1, a venom peptide from predatory marine snail T. variegata showed specific and selective cytotoxicity for murine liver cancer cells by binding to the tumor cell membrane and modulating TRPC6 and/or TRPV6 ion channels." (PMID 31627357, 2019). "Targeting TRPC6 in the treatment of liver cancer may be a new antitumor strategy, especially in combination with chemotherapy." (PMID 36187789, 2022). "The overexpression of TRPC6 causes a continuous increase in intracellular free calcium and regulates the EMT, HIF1-α signaling, and DNA damage repair mechanisms related to multidrug resistance to stimulate and enhance the resistance of liver cancer cells to multiple drugs." (PMID 36187789, 2022).
melanoma (3 papers, 2019 to 2023). A malignant, usually aggressive tumor composed of atypical, neoplastic melanocytes. "However, the blockage of the TRPC6 Ca++ channel or the use of Ca++ and Zn++ chelators do not hinder HPF cytostatic/cytotoxic activity, suggesting that damages induced in melanoma cells may pass through other pathways." (PMID 36674794, 2023).
metabolic syndrome (3 papers, 2017 to 2022). A cluster of metabolic risk factors for CARDIOVASCULAR DISEASES and TYPE 2 DIABETES MELLITUS. "Upregulated TRPC6 expression was detected in the smooth muscle layer of the coronary arteries isolated from metabolic syndrome pigs." (PMID 32872338, 2020). "The promoter regions of TRPC1 and TRPC6 possess half-site glucocorticoid/mineralocorticoid response elements driving the expression of these TRPC channels in metabolic syndrome, characterized by elevated plasma aldosterone." (PMID 28756533, 2017). "Previously, we reported that TRPC1 and TRPC6 expression is markedly elevated in metabolic syndrome pig coronary arteries." (PMID 28756533, 2017). "Thus, targeting TRPC6 may be a promising therapeutic strategy for renal fibrosis and immune cell infiltration in polygenic models for the human metabolic syndrome." (PMID 32872338, 2020). "In the present study, we hypothesized that this novel selective TRPC6 inhibitor (SH045) could ameliorate renal fibrogenesis in the New Zealand obese (NZO) mouse model, which is a polygenic model of metabolic syndrome." (PMID 35743312, 2022).
myocardial infarction (3 papers, 2013 to 2023). Gross necrosis of the myocardium, as a result of interruption of the blood supply to the area, as in coronary thrombosis. "In mice, global KO of Trpc6 results in increased mortality after myocardial infarction, however this is primarily due to the role Trpc6 plays in cardiac fibroblast activation, a process which is essential for early scar formation in order to avoid cardiac rupture." (PMID 38259319, 2023). "Because of the role TRPC6 plays in different cell types in mammals, it will be interesting to determine the effect that conditional, cardiomyocyte specific, deletion of Trpc6 has following myocardial infarction." (PMID 38259319, 2023). "On the one hand, TRPC6 appears to be necessary for cardiac scar formation post myocardial infarction, since TRPC6 null-mutant mice demonstrate a higher incidence of cardiac rupture, a lower recovery of function, a smaller wall scar and greater ventricular dilatation." (PMID 36277180, 2022). "Future research may reveal whether increased TRPC6 expression is involved in the facilitated mechanosensitivity of cardiomyocytes at the border zone in myocardial infarction." (PMID 23441631, 2013). "TRPC6 protein expression is increased in rat myocardial infarction." (PMID 23441631, 2013). "In contrast adult mice do not appear to upregulate the expression of Trpc6 following myocardial infarction." (PMID 38259319, 2023).
viral infection (3 papers, 2021 to 2024). "This study created TRPC6 overexpression models by virus infection in cultured podocytes and adriamycin injection in SD rats." (PMID 34906112, 2021).
acute lung injury (2 papers, 2017 to 2023). A condition of lung damage that is characterized by bilateral pulmonary infiltrates (pulmonary edema) rich in neutrophils, and in the absence of clinical heart failure. "Acute lung injury (ALI) is characterized by endothelial barrier disruption and associated inflammatory responses, and transient receptor potential cation channel 6 (TRPC6)—mediated Ca2+ influx is critical for endothelial hyperpermeability." (PMID 38069081, 2023). "Additionally, TRPC6 is critically involved in the regulation of pulmonary vascular permeability and lung edema formation during endotoxin or ischemia/reperfusion-induced acute lung injury." (PMID 28670316, 2017).
amyloid (2 papers, 2015 to 2022). "To further confirm the effect of TRPC6, we examined whether TRPC6 could reduce amyloid plaque in APP/PS1 mice with another genetic background." (PMID 26581893, 2015).
asthma (2 papers, 2019 to 2022). "In most of the cells, TRP channels are expressed, and strong evidence for an essential role in airway function and associated diseases, such as CF, asthma, fibrosis and edema was demonstrated for TRPA1, TRPC6, TRPM2, TRPM5, TRPM7, TRPV2, TRPV4 and TRPV6." (PMID 36139480, 2022).
channelopathies (2 papers, 2021 to 2025). "Summarizing, the LC-MS/MS method and exploratory pharmacokinetic data provide essential prerequisites for experimental pharmacological TRPC6 modulation and translational treatment of TRPC6 channelopathies." (PMID 33805686, 2021). "However, the understanding of TRPC6 channelopathies is still at the beginning stages." (PMID 33805686, 2021).
cystic fibrosis (2 papers, 2019 to 2023). Autosomal recessive disorder caused by pathogenic variants in the CFTR gene (cystic fibrosis transmembrane conductance regulator), which encodes a chloride and bicarbonate channel expressed in epithelial cells, and follow the diagnosis criteria. "In pulmonary cystic fibrosis, alveolar macrophage TRPC6 is associated with proton pump generation of transmembrane potential, thereby restoring phagocytic and bactericidal functions of damaged alveolar macrophages in CF." (PMID 37404813, 2023).